RNU6-187P (RNA, U6 small nuclear 187, pseudogene)
Gene: Small nuclear RNA gene on chromosome 2 (176,929,985 to 176,930,090, reverse strand). Ensembl gene ENSG00000206866.
Homologues: Orthologues: chimpanzee U6 (100% identical), macaque U6 (99% identical), mouse Gm24423 (88% identical), guinea pig U6 (87% identical), rat LOC120099391 (87% identical), mouse Gm22716 (86% identical), rat LOC120097299 (85% identical), mouse Gm23142 (82% identical), mouse Gm26240 (81% identical), mouse Gm23926 (75% identical), rat LOC120097194 (72% identical). Paralogues in human: RNU6-1075P (92% identical), RNU6-41P (92% identical), RNU6-1060P (92% identical), RNU6-116P (92% identical), RNU6-1011P (91% identical), RNU6-1124P (91% identical), RNU6-12P (91% identical), RNU6-13P (91% identical), RNU6-25P (91% identical), RNU6-29P (91% identical), RNU6-32P (91% identical), RNU6-33P (91% identical), and 1290 more.